FOXO3 (forkhead box O3)
Diseases named in the same sentence as FOXO3 in open-access papers (continued):
Sharing a sentence is not in itself a finding about the gene and the disease.
Sepsis (17 papers, 2011 to 2024). Sepsis is defined as life-threatening organ dysfunction caused by a dysregulated host response to infection. "Accordingly, we recruited ICU-acquired sepsis patients and grouped them according to their genotypes of rs12196996 and rs2232365, in the aim to study the association between circRNA_FOXO3 rs12196996 polymorphism or FOXO3 rs2232365 polymorphism and the survival or severity of ICU-acquired infection." (PMID 35156517, 2022). "In this study, the patients with ICU-acquired sepsis were recruited and divided into four groups based on their genotypes at circRNA_FOXO3 rs12196996 and FOXO3 rs2232365." (PMID 35156517, 2022). "In our study, we carried out qPCR to analyze the level of circRNA_FOXO3, miR-23a and FOXO3 mRNA in the peripheral blood of patients with ICU-acquired sepsis." (PMID 35156517, 2022). "Our results are in accordance with a previous study that revealed the downregulation of miR-34a in sepsis-induced acute lung injury through targeting fork head box O3 (FoxO3), resulting in the activation of autophagy." (PMID 34990478, 2022). "In addition, the M1 polarization and glycolysis of alveolar macrophage was induced by FoxO3-mediated activation of PFKFB3 in sepsis-related acute lung injury." (PMID 38725041, 2024). "Notably, the upregulation of UBXN6 in sepsis patients was negatively correlated with inflammatory gene profiles but positively correlated with the expression of Forkhead box O3, an autophagy-driving transcription factor." (PMID 39438692, 2024). "In this study, we demonstrated that the minor allele of rs12196996 polymorphism located in circRNA_FOXO3 and the minor allele of rs2232365 polymorphism located in FOXO3 mRNA collaboratively contributed to the increased survival and suppressed severity of ICU-acquired sepsis." (PMID 35156517, 2022). "In sepsis patients, UBXN6 levels were negatively correlated with inflammatory gene profiles but positively correlated with the levels of Forkhead box O3 (FOXO3) and several autophagy/mitophagy-related genes." (PMID 39438692, 2024). "Indeed, recent findings showed that AMPK activation upon sepsis or AICAR injection increased FOXO3, FOXO1 but not FOXO4 mRNA levels in skeletal muscle of mice." (PMID 22848740, 2012). "Different roles of FoxO1 and FoxO3 in insulin and AMPK signaling have been suggested in previous in vitro non-muscle cell studies and in rat sepsis-induced muscle wasting." (PMID 21483870, 2011).
acute myeloid leukemia (16 papers, 2015 to 2024). Acute myeloid leukemia (AML) is a group of neoplasms arising from precursor cells committed to the myeloid cell-line differentiation. "For example, high expression of FOXO3 is associated with a decreased overall survival in acute myeloid leukemia (AML)." (PMID 31488102, 2019). "Moreover, overexpression of FOXO3 is associated with reduced overall survival and progression-free survival in patients with acute myelogenous leukemia and with poor prognosis in patients with pancreatic ductal adenocarcinoma and glioblastoma." (PMID 34123834, 2021). "In this study, we will test the expression of Foxo3 and circ-Foxo3 in de novo acute myeloid leukemia (AML) patients to explore the relationship between Foxo3 gene and circ-Foxo3." (PMID 31533653, 2019). "In humans, FOXOs were originally discovered in rhabdomyosarcomas and acute myeloid leukemias, in which three members (FOXO1, FOXO3 and FOXO4) were identified due to the chromosomal translocations that produce fusion proteins." (PMID 30646603, 2019). "It has been reported that conditional deletion of FoxO1, FoxO3 and FoxO4 simultaneously results in the development of hemangiomas and thymic lymphomas, and IκB kinase represses FoxO3a activity to promote human breast tumorigenesis and acute myeloid leukemia (AML)." (PMID 26474173, 2015). "Importantly, FOXO3 is reported to be phosphorylated mainly by p-AKT along PI3K–AKT signaling and p-ERK through MAPK–ERK signaling in previous studies on cell survival and acute myeloid leukemia, respectively." (PMID 32123161, 2020).
ischemia (16 papers, 2012 to 2025). A hypoperfusion of the BLOOD through an organ or tissue caused by a PATHOLOGIC CONSTRICTION or obstruction of its BLOOD VESSELS, or an absence of BLOOD CIRCULATION. "The three hub genes, STAT3, NOTCH1, and FOXO3, which are crucial essential factors to regulate the vascular diseases, and closely associated with modulation of proliferation, migration, differentiation and ischemia in a wide range of vascular diseases." (PMID 34988135, 2021). "Combined deletion of FoxO1 and FoxO3 specifically in cardiomyocytes results in increased cardiac injury following acute ischemia and reperfusion in vivo, suggesting that FoxO1 and FoxO3 protect the heart from oxidative stress (Sengupta, Molkentin, Paik, DePinho, & Yutzey, 2011)." (PMID 31264342, 2019). "In addition, it remains to be explored whether the activation of FoxO3/SPHK1 signaling occurs during the ischemia phase or following reperfusion." (PMID 34051800, 2021). "On the other hand, FOXO3 knockout mice with hind limb ischemia showed an increase in capillary density 14 days after ischemia induction, indicating that FOXO3 is an important negative regulator of angiogenesis." (PMID 41002121, 2025).
Parkinson disease (16 papers, 2009 to 2025). A progressive degenerative disorder of the central nervous system characterized by loss of dopamine producing neurons in the substantia nigra and the presence of Lewy bodies in the substantia nigra and locus coeruleus. "In Parkinson's disease, inhibition of Foxo3 causes oxidative damage and is detrimental if the inhibition is too strong." (PMID 40859434, 2025). "It has been reported that an increase in FOXO3 activity causes neurodegenerative diseases such as Alzheimer’s and Parkinson’s." (PMID 30778283, 2019). "The FOXO3 activity pathway was also evaluated in this study due to its dysregulation in Parkinson’s disease (PD)." (PMID 37325771, 2023). "The stress response factor FOXO3 is neuroprotective in models of Huntington’s disease (HD), Parkinson’s disease and motor-neuron diseases." (PMID 28638078, 2017). "FOXO3 has been shown to control the accumulation of human α‐synuclein, a protein known to participate in the development of Parkinson's disease." (PMID 26643314, 2016). "Among the first three predicted TFs that may bind and affect the transcription of CTNNA2, Foxo3 was reported to be neuroprotective in neurodegenerative diseases like Parkinson's and Huntington's disease." (PMID 40859434, 2025). "In a study of Parkinson’s Disease, miR-182-5p and miR-183-5p were shown to mediate neuroprotection of dopaminergic (DA) neurons in vitro and in vivo by down-regulating the expression of FOXO3 and FOXO1 and enhancing PI3K-Akt signaling." (PMID 34572398, 2021).
myocardial ischemia (15 papers, 2015 to 2025). A disorder of cardiac function caused by insufficient blood flow to the muscle tissue of the heart. "miR-23a has been reported to decrease during myocardial ischemia–reperfusion (I/R) injury, which promotes oxidative stress and apoptosis; conversely, its overexpression mitigates apoptosis by inhibiting FoxO3 and BIM expression." (PMID 41301959, 2025). "And PARP1 silencing or specific inhibitors alleviated the promotion of FoxO3 activity upon starvation or myocardial ischemia, thus suppressing cardiac apoptosis and fibrosis." (PMID 30323296, 2018).
premature ovarian failure (15 papers, 2007 to 2025). "Mouse models deficient in FOXO3 show the premature activation of primordial follicles during the neonatal period, resulting in follicle loss and premature ovarian failure." (PMID 40428424, 2025). "Meanwhile, cisplatin treatment decreased PTEN levels and increased the phosphorylation and activation of key molecules in the PTEN/Akt/FOXO3 pathway causing follicular activation and resulting in premature ovarian failure." (PMID 36559263, 2022). "FoxO3-deficient mice exhibit early depletion of ovarian follicles, which is reminiscent of premature ovarian failure in women." (PMID 17201918, 2007). "A few years later, another study analyzed FOXO3 mutations in 114 Chinese women with premature ovarian failure and identified six new variants that might cause early follicle depletion." (PMID 34193292, 2021). "In women with premature ovarian insufficiency (POI) or premature ovarian failure (POF), mutation in FOXO3 genes was identified and lower FOXO3a expression in ovarian tissue was detected." (PMID 32849312, 2020). "This study is the first to show the involvement of the PTEN/Akt/FOXO3 pathway in premature ovarian failure after cisplatin treatment and the possibility of rescue through in vitro maturation." (PMID 26656301, 2015). "Foxo3 knockout leads to premature ovarian failure (POF) in mice." (PMID 28615648, 2017).
renal fibrosis (15 papers, 2015 to 2025). A final common manifestation of a wide variety of chronic kidney diseases characterized by glomerulosclerosis and tubulointerstitial fibrosis. "Additionally, luteolin has been found to reduce anemia caused by renal fibrosis through the SIRT1/FOXO3 pathway." (PMID 41334230, 2025). "Luteolin can reduce renal anemia caused by renal fibrosis by regulating SIRT1/FOXO3 pathway." (PMID 38403669, 2024). "In renal fibrosis, miR-342-5p has been revealed to target Ptch1 and inhibit its transcription factor FoxO3, leading to autophagy in the TGF-β1-stimulated TCMK-1 (mouse kidney) cells." (PMID 39379100, 2024). "miR-182 is expressed through direct binding to FOXO3 to promote apoptosis in ischemia–reperfusion-induced acute kidney injury; miR-122 enhances renal fibrosis, renal inflammation, and oxidative damage in hypertensive rats by inhibiting the expression of FOXO3." (PMID 37553608, 2023). "Based on the results of our study alone, it is difficult to conclude that FOXO3 has a beneficial effect on renal fibrosis and CKD." (PMID 36499744, 2022). "We found that the upregulation of FOXO3 by the miRNA−122−5p inhibitor had therapeutic potential for renal fibrosis." (PMID 36499744, 2022). "An miR−122−5p mimic enhanced renal fibrosis with the increased expression of TGFR2, whereas an miR−122−5p inhibitor suppressed renal fibrosis with the increased expression of FOXO3 (with the upregulation of the downstream genes, LC3)." (PMID 36499744, 2022). "Because LC3 is involved in autophagy responses, our results are consistent with previous reports explaining the mechanisms whereby FOXO3 ameliorated renal fibrosis and CKD." (PMID 36499744, 2022). "As mentioned in the Results section, the beneficial effects of FOXO3 on renal fibrosis and CKD were recently reported." (PMID 36499744, 2022). "However, our results are consistent with previous reports and support the reported positive effect of FOXO3 on renal fibrosis and CKD." (PMID 36499744, 2022). "Therefore, a deeper understanding and confirmation of how FOXO3 ameliorates renal fibrosis are needed." (PMID 36499744, 2022). "In previous studies, FOXO3 was reported to have a protective role against renal fibrosis and CKD." (PMID 36499744, 2022). "FOXO3 appears to be protective against renal fibrosis and CKD." (PMID 36499744, 2022). "The study findings suggested that TGFBR2 (a pro-fibrotic factor) might be involved in the mechanism by which the miR−122−5p mimic promotes renal fibrosis and FOXO3 (an anti-fibrotic factor) might be involved in the mechanism by which the miR−122−5p inhibitor suppresses renal fibrosis." (PMID 36499744, 2022). "FOXO3 inactivation positively correlates with cumulating of collagens and up‐regulation of α‐SMA in the renal fibrosis." (PMID 32705806, 2020). "Besides, activated FoxO3 decreases IL6 levels via decrement of gene expression and protects against renal fibrosis." (PMID 39906624, 2025).
Skeletal muscle atrophy (15 papers, 2009 to 2025). The presence of skeletal muscular atrophy (which is also known as amyotrophy). "We hypothesise that the increased levels of miR‐142‐5p, through suppression of FOXO3, may lead to reduced muscular atrophy and improved motor function acquirement." (PMID 35584175, 2022).
cervical carcinoma (14 papers, 2013 to 2026). A carcinoma arising from either the exocervical squamous epithelium or the endocervical glandular epithelium. "Resveratrol induced apoptosis in cervical cancer HeLa cells by activating FOXO3 and promoting its nuclear translocation." (PMID 39334758, 2024). "Moreover, FOXO3, which is considered to be a regulator for FOXM1, has been shown to participate in the development of cervical cancer and the lactate-rich microenvironment during HPV infection in cervical squamous carcinoma cell." (PMID 36900213, 2023).
coronary heart disease (14 papers, 2014 to 2025). "The Circ-FOXO3 flanking intron rs12196996 polymorphism affects Circ-FOXO3 expression and raises the risk of coronary artery disease." (PMID 35741795, 2022). "The first study on FOXO3 genetic variants implicated in longevity revealed that homozygosity for the rs2802292 G-allele is associated with a lower prevalence of coronary artery disease and cancer." (PMID 31303978, 2019).
lymph node metastasis (14 papers, 2010 to 2024). "And low FOXO3 levels correlated with the increased lymph node metastasis ratios and advanced clinical stages." (PMID 30514328, 2018).
rhabdomyosarcoma (14 papers, 2012 to 2025). A rare aggressive malignant mesenchymal neoplasm arising from skeletal muscle. "The FoxO family includes FoxO1 Forkhead in Rhabdomyosarcoma), FoxO3 (Forkhead in Rhabdomyosarcoma-like 1), FoxO4 (Acute lymphoid leukemia fused gene), and FoxO6 proteins." (PMID 40881129, 2025). "FOXO3 has a role in different diseases such as Rhabdomyosarcoma and secondary acute leukemia, and it is also a regulator of regulatory T-cell differentiation." (PMID 40453647, 2025). "In a similar manner to the FOXO1 chromosomal translocation in alveolar rhabdomyosarcoma, FOXO3 (also known as FKHRL1) and FOXO4 (also known as AFX) are translocated to the MLL gene in mixed lineage leukaemia (MLL), an aggressive paediatric blood cancer." (PMID 32372224, 2020). "The mammalian Forkhead box O (FoxO) family includes four members expressed nearly in all tissues: FoxO1 (forkhead in rhabdomyosarcoma, FKHR), FoxO3 (forkhead in rhabdomyosarcoma like protein 1, FKHRL1), FoxO4 (acute leukemia fusion gene located in chromosome X, AFX), and FoxO6." (PMID 32244542, 2020).
triple-negative breast carcinoma (14 papers, 2016 to 2025). An invasive breast carcinoma which is negative for expression of estrogen receptor (ER), progesterone receptor (PR), and human epidermal growth factor receptor 2 (HER2). "In agreement with our data, PIP has been reported to inhibit the PI3K/AKT axis in human triple-negative breast cancer cells and to activate FOXO3, inducing the expression of the FOXO target gene BCL2 Like 11 (BIM) in HeLa cells." (PMID 33316942, 2020).
esophageal squamous cell carcinoma (13 papers, 2015 to 2025). Esophageal squamous cell carcinoma (ESCC) is a type of esophageal carcinoma (EC) that can affect any part of the esophagus, but is usually located in the upper or middle third. "Overexpression of circ-FOXO3 suppressed cell growth, migration and invasion through sponging miR-23 in esophageal squamous cell cancer, while circ-FOXO3 relieved blood-brain barrier by sequestering mTOR and E2F1 in ischemia/reperfusion injury." (PMID 36506538, 2022). "Notably, miR-10b-3p can inhibit the expression of FOXO3 protein by targeting the 3′-untranslated region, which promotes cell proliferation, colony formation, and migration and invasion of esophageal squamous cell carcinoma." (PMID 40191422, 2025). "Through AKT signaling, RAP1A promotes metastasis in esophageal squamous cell carcinoma (ESCC), and an aggressive phenotype in colorectal cancer through PTEN/FOXO3/CCND1 pathway." (PMID 33958005, 2021).
Huntington disease (13 papers, 2014 to 2025). Huntington disease (HD) is a rare neurodegenerative disorder of the central nervous system characterized by unwanted choreatic movements, behavioral and psychiatric disturbances and dementia. "Furthermore, FOXO3a contributes to neuroprotection by Sirt1 in a striatal cell model of Huntington’s disease and moderate FOXO3 activation was recently shown to oppose α-synuclein accumulation and proteotoxicity." (PMID 26419537, 2015).
lymphoma (13 papers, 2015 to 2025). A malignant (clonal) proliferation of B- lymphocytes or T- lymphocytes which involves the lymph nodes, bone marrow and/or extranodal sites. "The transcription of RASIP1 was inhibited by FOXO3, a lymphoma-suppressing transcription factor." (PMID 36967521, 2023). "FOXF1, FOXK2, FOXO1, FOXO3, and FOXP1 were differentially expressed in at least five subtypes of lymphoma." (PMID 36292640, 2022). "Foxo1 and Foxo3 in CD4+ T cells are the most important among Foxo family members because the T-DKO mice are lethal from eight weeks of age due to immunological disturbance, leading to lymphoma, enteritis, and digestive malabsorption." (PMID 31756626, 2019). "In contrast to normal thymus, Lx+ lymphomas exhibited reduced p27 RNA expression, without corresponding changes in miR-106a~363, Foxo3 or Foxo4 RNA." (PMID 28881594, 2017). "In the Eμ-myc model, expansion of the pre-B-cell pool, although modest, may contribute to accelerated lymphoma development in the absence of FoxO3." (PMID 26764572, 2016). "In the absence of FoxO3, myeloid tumours arose more rapidly in vavP-MYC10 mice and pre-B and B lymphomas arose more rapidly in Eμ-myc transgenic mice." (PMID 26764572, 2016).